HSPA9 (heat shock protein family A (Hsp70) member 9)
Description:
Mitochondrial chaperone that plays a key role in mitochondrial protein import, folding, and assembly. Plays an essential role in the protein quality control system, the correct folding of proteins, the re-folding of misfolded proteins, and the targeting of proteins for subsequent degradation. These processes are achieved through cycles of ATP binding, ATP hydrolysis, and ADP release, mediated by co-chaperones. In mitochondria, it associates with the TIM (translocase of the inner membrane) protein complex to assist in the import and folding of mitochondrial proteins (By similarity). Plays an important role in mitochondrial iron-sulfur cluster (ISC) biogenesis, interacts with and stabilizes ISC cluster assembly proteins FXN, NFU1, NFS1 and ISCU. Regulates erythropoiesis via stabilization of ISC assembly. Regulates mitochondrial calcium-dependent apoptosis by coupling two calcium channels, ITPR1 and VDAC1, at the mitochondria-associated endoplasmic reticulum (ER) membrane to facilitate calcium transport from the ER lumen to the mitochondria intermembrane space, providing calcium for the downstream calcium channel MCU, which releases it into the mitochondrial matrix (By similarity). Although primarily located in the mitochondria, it is also found in other cellular compartments. In the cytosol, it associates with proteins involved in signaling, apoptosis, or senescence. May play a role in the control of cell proliferation and cellular aging (By similarity). Protects against reactive oxygen species (ROS) (By similarity). Extracellular HSPA9 plays a cytoprotective role by preventing cell lysis following immune attack by the membrane attack complex by disrupting formation of the complex.
Synonyms: GRP-75; MOT; PBP74; GRP75; HSPA9B; mot-2; mthsp75; CRP40; CSA; EVPLS; HEL-S-124m; MOT2; SAAN; SIDBA4
Tractability: Small molecule: a structure with a bound ligand is known; a high-quality ligand is known. PROTAC: ubiquitination databases record sites on it; its protein half-life has been measured; a small molecule that binds it is known.
Gene: Protein-coding gene on chromosome 5 (138,553,756 to 138,575,675, reverse strand). Ensembl gene ENSG00000113013.
Subcellular location: Mitochondrion; Nucleus, nucleolus; Cytoplasm; Mitochondrion matrix
Subcellular location (Human Protein Atlas): Mitochondria
Pathways (Reactome):
Cellular responses to stimuli: Mitochondrial unfolded protein response (UPRmt); Regulation of HSF1-mediated heat shock response
Metabolism: Complex I biogenesis; Complex III assembly
Immune System: Gene and protein expression by JAK-STAT signaling after Interleukin-12 stimulation
Metabolism of proteins: Mitochondrial protein degradation
Organelle biogenesis and maintenance: Cristae formation
Protein localization: Mitochondrial protein import
Gene Ontology:
Molecular function: ATP hydrolysis activity; protein binding; RNA binding; ubiquitin protein ligase binding; heat shock protein binding; protein folding chaperone; ATP binding; enzyme binding; fibroblast growth factor binding; protein-folding chaperone binding
Biological process: erythrocyte differentiation; iron-sulfur cluster assembly; negative regulation of erythrocyte differentiation; regulation of erythrocyte differentiation; calcium import into the mitochondrion; inner mitochondrial membrane organization; intracellular protein transport; negative regulation of apoptotic process; protein import into mitochondrial matrix; protein refolding; cellular response to interleukin-1; negative regulation of hematopoietic stem cell differentiation; negative regulation of hemopoiesis; protein folding; response to folic acid; response to thyroxine; response to toxic substance
Cellular component: cytoplasm; extracellular exosome; focal adhesion; MIB complex; mitochondrial matrix; mitochondrial nucleoid; mitochondrion; SAM complex; mitochondrial inner membrane; PAM complex, Tim23 associated import motor; TIM23 mitochondrial import inner membrane translocase complex; nucleolus
Genetic constraint (gnomAD): Loss-of-function variants: 25 observed, 66.49 expected, observed/expected ratio (o/e) 0.38, 90% interval 0.27 to 0.52. The upper end of that interval is the gene's LOEUF score, 0.52, which puts it in group 2 of 6, group 1 being the genes least tolerant of losing a copy. Missense variants: 605 observed, 774.55 expected, observed/expected ratio (o/e) 0.78, 90% interval 0.73 to 0.83. Synonymous variants: 265 observed, 270.31 expected, observed/expected ratio (o/e) 0.98, 90% interval 0.89 to 1.09.
Homologues: Orthologues: chimpanzee HSPA9 (99% identical), macaque HSPA9 (99% identical), dog HSPA9 (99% identical), rabbit HSPA9 (99% identical), guinea pig HSPA9 (98% identical), mouse Hspa9 (98% identical), pig HSPA9 (98% identical), rat Hspa9 (98% identical), zebrafish hspa9 (87% identical), tropical clawed frog hspa9 (86% identical), Drosophila melanogaster Hsc70-5 (75% identical), Caenorhabditis elegans hsp-6 (73% identical). Paralogues in human: HSPA8 (50% identical), HSPA5 (49% identical), HSPA6 (48% identical), HSPA1L (47% identical), HSPA2 (47% identical), HSPA1A (47% identical), HSPA1B (47% identical), HSPA4 (26% identical), HSPA4L (26% identical), HSPH1 (25% identical), HSPA13 (24% identical), HSPA14 (23% identical), and 1 more.
Diseases named in the same sentence as HSPA9 in open-access papers:
HSPA9 is named in the same sentence as 150 diseases in open-access papers, as found by Europe PMC text mining. Sharing a sentence is not in itself a finding about the gene and the disease. The quoted sentences say what the papers report.
breast carcinoma (26 papers, 2008 to 2024). "Besides, the over‐expression of HSPA9 promoted invasion and metastasis of breast cancer and associated with histological grade, clinical stage and lymph node metastasis." (PMID 33191617, 2021). "Experimental approaches, including CCK-8, Transwell, and wound healing assays, revealed that the protein HSPA9 restricts the growth and movement of breast cancer cells." (PMID 38312844, 2024). "Compared to the control group, the si-HSPA9 group of breast cancer cells exhibited a pronounced attenuation in proliferation over a specified time period." (PMID 38312844, 2024). "Following the suppression of HSPA9 expression, a significant accumulation of sphingolipids, including ceramide, was observed in breast cancer cells as compared to the control group." (PMID 38312844, 2024). "By focusing on the essential gene HSPA9 within the cancer-immunity cycle, this strategy has the potential to significantly improve the efficacy of treatments against breast cancer." (PMID 38312844, 2024). "At the same time, immunofluorescence experiment showed that HN1L and HSPA9 were co‐expressed in breast cancer cells." (PMID 33191617, 2021). "The review is dedicated to the role of members of the heat shock protein 70 subfamily (HSP70s or HSPA), mainly inducible HSP70, glucose-regulated protein 78 (GRP78 or HSPA5) and GRP75 (HSPA9 or mortalin), in the development and pathogenesis of breast cancer." (PMID 34943954, 2021). "Multiple heat shock proteins, including Hsp90AA1, Hsp90AB1, TRAP1, HspA5, HspB1, HspE1, HspD1, HspA1B, HspA8, HspA9, and HspA4, were significantly upregulated in breast cancer tissue." (PMID 31921692, 2019). "In this study, by constructing PCDHGB7 knockdown and overexpression models and HSPA9 knockdown breast carcinoma cell models, we confirmed the positive correlation between the PCDHGB7 level and the cell's chemosensitivity to carboplatin." (PMID 31379979, 2019). "Heat shock proteins showed the most significant change of all the upregulated domains, with Hsp90AA1, Hsp90AB1, TRAP1, HspA5, HspB1, HspE1, HspD1, HspA1B, HspA8, HspA9, and HspA4 identified in breast cancer tissue." (PMID 31921692, 2019). "Hsp90AA1, Hsp90AB1, TRAP1, HspA5, HspB1, HspE1, HspD1, HspA1B, HspA8, HspA9, and HspA4 were validated as potential biomarkers for breast cancer tissue." (PMID 31921692, 2019). "Our results demonstrated that PCDHGB7 inhibits HSPA9 and increases chemosensitivity to carboplatin via inducing apoptosis in breast cancer." (PMID 31379979, 2019). "An elevated level of HSPA9, with reduced caspase-3 and aberrant release of cytochrome c, has been reported to be responsible for the chemoresistance to cisplatin in breast cancer cells." (PMID 31379979, 2019). "In our study, we also detected the HSPA9 mRNA levels in breast cancer cells (Hs578T and BT549) with PCDHGB7 knockdown and overexpression." (PMID 31379979, 2019). "In line with our hypothesis, we observed a significant inhibition of breast cancer cell proliferation starting at 48 hours after HSPA9 interference." (PMID 38312844, 2024).
breast carcinoma (continued). "Additionally, HSPA9 downregulates ceramide expression, weakening ceramide’s inhibitory effect on tumor cell migration and leading to distant metastasis of breast cancer cells." (PMID 38312844, 2024). "Considering the impact of ceramide on tumor cell proliferation, we conducted CCK-8 experiments to observe whether HSPA9 inhibition would slow down breast cancer cell proliferation." (PMID 38312844, 2024). "Additionally, it has been demonstrated that overexpressing Hspa9 is adequate to induce breast cancer cells to be more aggressive." (PMID 38138960, 2023). "HSPA9 expression was positive associated with histological grade, pathological stage and lymphatic metastasis in breast cancer, and its expression was negative associated with shorter disease-free survival and overall survival." (PMID 34712697, 2021). "Results showed that HN1L and HSPA9 were co‐expressed and interacted in breast cancer cells which were in line with our hypothesis." (PMID 33191617, 2021). "HSPA9, a member of the heat shock protein family, regulates Raf/MEK/extracellular signal-regulated kinase (ERK) and is associated with tumorigenesis, especially drug resistance in breast cancer treatment." (PMID 33194682, 2020). "PCDHGB7 and HSPA9 represent potential therapeutic targets for chemosensitivity in breast cancer." (PMID 31379979, 2019). "PCDHGB7 and HSPA9 potentially represent novel targets of chemotherapy in breast cancer." (PMID 31379979, 2019). "This discovery further elucidates how the high expression of cuproptosis-CICs genes in breast cancer patients may lead to a poor prognosis by upregulating HSPA9, thereby shaping an immune-suppressive microenvironment and enhancing distant metastasis of breast cancer cells." (PMID 38312844, 2024). "Therefore, we hypothesize that HSPA9 may inhibit ceramide formation, subsequently promoting breast cancer cell motility and resistance to immune therapies." (PMID 38312844, 2024). "Mechanistically, HN1L interacted with HSPA9 and affected the expression of HMGB1, playing a key role in promoting the invasion and metastasis of breast cancer cell." (PMID 33191617, 2021). "Although our study offers new insight into the mechanisms of HN1L in breast cancer metastasis, the specific regulatory mechanisms of the interactions among HN1L, HSPA9 and HMGB1 need further study." (PMID 33191617, 2021). "Like TFR1, shRNA knockdown of HSPA9 results in a major proliferation inhibition of breast cancer and, particularly, of melanoma cells, regardless of MEMO1 expression level." (PMID 38640016, 2024). "Moreover, in the case of control samples, we found overexpression of the proteins: PRDX2, PRDX5 and AIFM1 involved in ROS; TUSC2 in PMM; ALKBH7, RHOT1, SAMM50, IMMT and HSPA9 in the MMO; and FUNDC2 in MIT compared to luminal A and basal-like breast cancer tumors." (PMID 35327574, 2022). "Considering that HSPA9 is involved in cell senescence and HMGB1 is one of the markers of cell senescence, we hypothesize that HNIL may interact with HSPA9 and participate in breast cancer cell invasion and metastasis mediated by HMGB1." (PMID 33191617, 2021).
hepatocellular carcinoma (16 papers, 2014 to 2024). A malignant tumor that arises from hepatocytes. "Numerous malignancies, including leukemia, brain cancer, colorectal adenocarcinoma and hepatocellular carcinoma, have been linked to increased expression of Hspa9." (PMID 38138960, 2023). "Specifically, HSPA9 was associated with metastasis of hepatocellular carcinoma (HCC), and overexpression of HSPA9 increased the malignancy and aggressive behavior of HCC." (PMID 32489334, 2020). "HSPA9 is overexpressed in numerous types of tumors and is involved in carcinogenesis and progression processes, including hepatocellular carcinoma metastasis." (PMID 34063343, 2021).
colon carcinoma (11 papers, 2008 to 2024). "In conclusion, the increased expression of HSPA1A1, HSPA1B, and HSPA7 was associated with poor prognosis, and HSPA9 was related to favorable prognosis for colon cancer." (PMID 34765552, 2021). "In summary, the increased expressions of HSPA1A1, HSPA1B, and HSPA7 were associated with poor prognosis, while that of HSPA9 was related to favorable prognosis for colon cancer patients." (PMID 34765552, 2021). "We found that increased expressions of HSPA1A1, HSPA1B, and HSPA7 were associated with poor prognosis, while that of HSPA9 was related to favorable prognosis for colon cancer patients." (PMID 34765552, 2021). "Our study indicated that increased HSPA9 expression was associated with favorable survival in colon cancer." (PMID 34765552, 2021). "Methylation of HSPA1A and HSPA9 was also analyzed, and it was found that the methylation of the HSPA1A promoter was significantly increased, and the methylation of the HSPA9 promoter was significantly decreased in colon cancer tissues." (PMID 34765552, 2021). "The expression difference of HSPA1A/HSPA1B/HSPA7/HSPA9 was verified in colon cancer cell lines and colonic epithelial cells." (PMID 34765552, 2021). "Results showed that promoter methylation of the HSPA1A gene in colon cancer tissues was significantly higher than normal tissues (P<0.001), and methylation of HSPA9 was significantly lower in colon cancer tissues (P<0.001)." (PMID 34765552, 2021). "Results showed that HSPA1A protein was decreased (P<0.001) and HSPA9 was increased (P<0.001) in colon cancer tissues." (PMID 34765552, 2021). "To verify the expression difference of HSPA1A/HSA1B/HSPA7/HSPA9 in the TCGA database, we compared the expression of these genes in colon cancer cells (HCT116 and HT29) and colonic epithelial cells (CP-H040)." (PMID 34765552, 2021). "The results were consistent with the results from the TCGA database, showing that HSPA1A was decreased and HSPA9 was increased in colon cancer." (PMID 34765552, 2021). "Univariate regression analysis was performed to explore the correlation of HSPA1A, HSPA1B, HSPA7, and HSPA9 expression with survival in colon cancer patients." (PMID 34765552, 2021). "We found that HSPA1A promoter methylation was significantly increased and HSPA9 promoter methylation was significantly decreased in colon cancer." (PMID 34765552, 2021). "A proteomic approach for identifying cellular proteins interacting with UBXN2A in a HCT116 colon cancer cell line revealed UBXN2A binds to mortalin-2 (GRP75, HSPA9, mot-2) protein." (PMID 27754413, 2016). "HSAP1B and HSPA9 were upregulated in colon cancer cell lines." (PMID 34765552, 2021). "Furthermore, GO ontology analysis was performed to screen the signaling pathways related to HSPA1A, HSPA1B, HSPA7, and HSPA9 in colon cancer." (PMID 34765552, 2021). "To explore whether downregulation of HSPA1A and upregulation of HSPA9 in colon cancer were related to DNA methylation, we analyzed the methylation of HSPA1A and HSPA9 promoters." (PMID 34765552, 2021). "The HSPA9 protein is one of the markers of a colon cancer stem cell population." (PMID 25379943, 2014). "HSPA9 may participate in the regulation of channel activity of colon cancer." (PMID 34765552, 2021). "Colon cancer cell lines also showed increased expression of HSPA1B and HSPA9 and decreased expression of HSPA1A and HSPA7." (PMID 34765552, 2021). "The relationships between HSPA1A and HSPA9 expression and survival were validated in the GEO dataset, and the HSPA1A and HSPA9 protein expression differences between colon cancer tissues and normal tissues were validated in the UALCAN database." (PMID 34765552, 2021). "It should be noticed that HSPA9 was elevated in colon cancer tissues in comparison with nontumor tissues." (PMID 34765552, 2021). "The result gave a clue that HSPA9 may be related to the tumorigenesis rather than the progression of colon cancer." (PMID 34765552, 2021).
colon carcinoma (continued). "However, there was no report about HSPA9 expression and its prognostic value in colon cancer." (PMID 34765552, 2021).
Parkinson disease (11 papers, 2013 to 2025). A progressive degenerative disorder of the central nervous system characterized by loss of dopamine producing neurons in the substantia nigra and the presence of Lewy bodies in the substantia nigra and locus coeruleus. "Mutations in HSPA9 may contribute to the risk of developing Parkinson’s disease." (PMID 36107978, 2022). "HSPA9 and SNAP91 are associated with neurodegenerative diseases, including Parkinson’s and Alzheimer’s diseases, emphasizing their roles in physiological aging and age-related disease progression." (PMID 41162879, 2025). "Other investigators have investigated a possible role of HSPA9 in the pathogenesis of Parkinson disease, based on the physical and functional relationship of HSPA9 (often referred to as mortalin in that literature) with parkins." (PMID 26598328, 2015). "A study about Parkinson’s disease revealed that member 9 of the 70 kDa Heat Shock Protein (HSPA9) might be a potential interactant of ACAT2 by tandem affinity purification/mass spectra." (PMID 38178203, 2024).
ovarian carcinoma (10 papers, 2018 to 2025). A malignant neoplasm originating from the surface ovarian epithelium. "Meanwhile, researchers discovered that the overexpression of HSPA9/GRP75 notably enhanced macropinocytosis in ovarian cancer cells, thereby synergizing with Tat-pDNA-Ca2+ nanoparticles to significantly amplify the cytotoxic effects on tumor cells." (PMID 39817564, 2025). "Notably, HSPA9, also known as GRP75, controls cisplatin resistance in patients with ovarian cancer by facilitating the integrity of the mitochondria-associated ER membrane (MAM)." (PMID 40362252, 2025).